IL12B (interleukin 12B)
Description:
Cytokine that can act as a growth factor for activated T and NK cells, enhance the lytic activity of NK/lymphokine-activated killer cells, and stimulate the production of IFN-gamma by resting PBMC. Associates with IL23A to form the IL-23 interleukin, a heterodimeric cytokine which functions in innate and adaptive immunity. IL-23 may constitute with IL-17 an acute response to infection in peripheral tissues. IL-23 binds to a heterodimeric receptor complex composed of IL12RB1 and IL23R, activates the Jak-Stat signaling cascade, stimulates memory rather than naive T-cells and promotes production of pro-inflammatory cytokines. IL-23 induces autoimmune inflammation and thus may be responsible for autoimmune inflammatory diseases and may be important for tumorigenesis.
Synonyms: IL-12B; NKSF2; CLMF; NKSF; CLMF2; IMD28; IMD29
Tractability: Small molecule: a structure with a bound ligand is known; it has a binding pocket of medium quality. Antibody: an approved drug acts on it; its Gene Ontology location is reachable by antibodies, with high confidence; UniProt places it where antibodies can reach, with medium confidence; UniProt predicts a signal peptide or a membrane-spanning region.
Target class: Secreted protein
Gene: Protein-coding gene on chromosome 5 (159,314,780 to 159,330,863, reverse strand). Ensembl gene ENSG00000113302.
Subcellular location: Secreted
Pathways (Reactome):
Immune System: Interleukin-10 signaling; Interleukin-12 signaling; Interleukin-23 signaling; Interleukin-4 and Interleukin-13 signaling
Gene Ontology:
Molecular function: cytokine activity; growth factor activity; identical protein binding; interleukin-12 alpha subunit binding; interleukin-23 receptor binding; protein binding; protein heterodimerization activity; interleukin-12 receptor binding; cytokine receptor activity; cytokine receptor binding; protein-containing complex binding
Biological process: cell migration; cell surface receptor signaling pathway via JAK-STAT; defense response to Gram-negative bacterium; interleukin-12-mediated signaling pathway; interleukin-23-mediated signaling pathway; natural killer cell activation; negative regulation of blood vessel endothelial cell proliferation involved in sprouting angiogenesis; negative regulation of interleukin-10 production; negative regulation of interleukin-17 production; negative regulation of protein secretion; negative regulation of smooth muscle cell proliferation; negative regulation of vascular endothelial growth factor signaling pathway; positive regulation of activated T cell proliferation; positive regulation of cell adhesion; positive regulation of defense response to virus by host; positive regulation of granulocyte macrophage colony-stimulating factor production; positive regulation of interleukin-10 production; positive regulation of interleukin-12 production; positive regulation of interleukin-17 production; positive regulation of lymphocyte proliferation; positive regulation of mononuclear cell proliferation; positive regulation of natural killer cell activation; positive regulation of natural killer cell mediated cytotoxicity directed against tumor cell target; positive regulation of natural killer cell proliferation; positive regulation of NK T cell activation; and 23 more
Cellular component: extracellular region; interleukin-12 complex; interleukin-23 complex; cytosol; endoplasmic reticulum lumen; late endosome lumen; cell surface; cytoplasm; endosome lumen; membrane
Genetic constraint (gnomAD): Loss-of-function variants: 26 observed, 36.11 expected, observed/expected ratio (o/e) 0.72, 90% interval 0.53 to 1. The upper end of that interval is the gene's LOEUF score, 1, which puts it in group 4 of 6, group 1 being the genes least tolerant of losing a copy. Missense variants: 329 observed, 397.16 expected, observed/expected ratio (o/e) 0.83, 90% interval 0.76 to 0.91. Synonymous variants: 135 observed, 154.57 expected, observed/expected ratio (o/e) 0.87, 90% interval 0.76 to 1.01.
Homologues: Orthologues: chimpanzee IL12B (99% identical), macaque IL12B (96% identical), dog IL12B (85% identical), pig IL12B (83% identical), rabbit IL12B (81% identical), guinea pig IL12B (79% identical), mouse Il12b (68% identical), rat Il12b (68% identical), tropical clawed frog il12b (28% identical), zebrafish il12ba (25% identical), zebrafish il12bb (23% identical).
Diseases named in the same sentence as IL12B in open-access papers:
IL12B is named in the same sentence as 192 diseases in open-access papers, as found by Europe PMC text mining. Sharing a sentence is not in itself a finding about the gene and the disease. The quoted sentences say what the papers report.
psoriasis (91 papers, 2008 to 2026). An autoimmune condition characterized by red, well-delineated plaques with silvery scales that are usually on the extensor surfaces and scalp. "The polymorphic region, IL-12B, rs3212227 is strongly associated with psoriasis and plays a crucial role in disease pathogenesis." (PMID 41596568, 2026). "Studies have shown that polymorphisms in the IL-12B gene are associated with various immune-related disorders, including psoriasis, RA, or certain cancers." (PMID 41596568, 2026). "Variants in the IL23R and IL12B genes have been associated with psoriasis susceptibility; however, data from Eastern European populations remains scarce." (PMID 42073384, 2026). "Their analysis revealed significant associations between psoriasis and the two IL12B SNPs, specifically rs3212227 and rs6887695." (PMID 40343299, 2025). "In psoriasis, the role of IL12B was demonstrated in a large multi-stage genetic association study performed in white North American cohorts." (PMID 41465136, 2025). "In psoriasis, IL12B promotes pathogenic IL-23 signaling that drives Th17-mediated skin inflammation, whereas in AD, IL12B variation influences IL-12–dependent neuroinflammatory pathways and modulates susceptibility to cognitive decline." (PMID 41465136, 2025). "Genetic variants within the major histocompatibility complex (MHC) and the TNIP1 and IL12B psoriasis susceptibility loci were associated with severe disease at genome-wide significance (P < 5.0 × 10-8)." (PMID 41408349, 2025). "GWAS have identified over 40 regions associated with psoriasis, including essential genes such as IL12B, IL23R, and IL23A, underscoring the critical role of the IL-23/Th17 axis." (PMID 39364475, 2024). "For example, mutations in the IL-12B, IL-23R, and IL-23A genes are associated with both susceptibility to psoriasis and an increased risk of developing diabetes." (PMID 38179048, 2023). "Previous research has found that in people with parents suffering from psoriasis are easier to suffer from this disease, several psoriasis susceptibility genes have been identified, including HLA-Cw6, IL12B, IL23R, and LCE3B/3C." (PMID 37497220, 2023). "To date, >70 psoriasis susceptibility loci have been identified, including HLA-Cw6, IL12B, IL23R, and LCE3B/3C." (PMID 35707771, 2022). "Genetic variations in IL12B are associated with psoriasis in a cohort of Danish patients, while SNPs in IL12B decrease the risk of developing AD." (PMID 35677926, 2022). "Unlike the structurally related pathogenic cytokine IL-23 p19 (IL-23A)/p40 (IL-12B), IL-12 was shown to have a regulatory function by restraining the invasion of IL-17-committed γδ T (γδ T17) cells in an imiquimod-induced psoriasis mouse model." (PMID 36110854, 2022). "Intriguingly, similar findings concerning the association of psoriasis with the IL12B and IL23R gene polymorphisms were documented in previous studies." (PMID 34680995, 2021). "The IL12/23 psoriasis pivotal pathway genes variants (IL12B and IL23R) also showed some association with DM-2 in a Spanish cohort." (PMID 34445769, 2021). "In an Egyptian cohort, the interaction of the single nucleotide polymorphisms rs610604 (IL-12B) and rs11209026 (IL-23R) showed a significant association with psoriasis." (PMID 33408595, 2020). "The genome-wide association study (GWAS) on psoriasis risk genetic loci also indicated that IL12B and IL23R are specifically susceptible genes associated with psoriasis." (PMID 31454926, 2019). "It informed the development of ustekinumab, a drug which targets the p40 subunit shared by IL-12 and IL-23 (SNPs in IL12B which encodes p40 are associated with psoriasis susceptibility)." (PMID 31130981, 2019). "Thirteen SNPs near IL12B (5q33.3) are associated with multiple sclerosis, psoriasis, primary biliary cholangitis, while the region’s associations extend to other autoimmune diseases (CD, UC, psoriatic arthritis, and ankylosing spondylitis)." (PMID 29309429, 2018).
psoriasis (continued). "Among a cohort of Danish patients with moderate-to-severe psoriasis, two SNPs in the IL12B and TNF genes were associated with susceptibility of psoriasis." (PMID 29389950, 2018). "Aside from the MHC components, also a few other genes, specifically those encoding interleukin 23 receptor (IL-23R) and interleukin 12B (IL-12B) were implicated in the pathogenesis of both psoriasis and IBD." (PMID 28905102, 2017). "The key role of this axis in psoriasis pathogenesis is strongly supported by the association between IL-23R, IL-12B, and IL-23A gene variants and psoriasis susceptibility." (PMID 27595115, 2016). "It is also a genetic-related disease, and the Genome Wide Association Study (GWAS) has identified many Psoriasis susceptibility gene loci (PSORs), including Human Leukocyte Antigen (HLA-C) (rs10484544) and interleukin-12b (IL-12b) (rs3212227)." (PMID 26691862, 2015). "SNP rs2288831 is in complete LD with rs3212227 located in the 3′-untranslated region (3′UTR) of IL12B, and this proxy SNP was reported to be associated with psoriasis in a large-scale association study, confirming the results of a previous study." (PMID 26063326, 2015). "Similar result from studying SNP rs6887695 in IL12B showed that the minor allele C was a protective factor from psoriasis." (PMID 24971308, 2014). "Our results showed that the IL12B gene was associated with psoriasis in Chinese at genotypic level (P < 0.05), which is in line with the findings from European studies." (PMID 24971308, 2014). "The data confirm previous associations between IL-12B gene polymorphisms and several autoimmune diseases such as ankylosing spondylitis and psoriasis." (PMID 24859272, 2014). "Recent studies indicated that a genetic aberration of the IL-12B gene is associated with several autoimmune diseases such as ankylosing spondylitis (AS) and psoriasis." (PMID 24859272, 2014). "Polymorphisms in IL23R and IL12B have been associated with susceptibility to psoriasis in both Caucasian and Asian patients." (PMID 24069534, 2013). "Interleukin 23 receptor (IL23R), IL12B, and the human leukocyte antigen Cw6 (HLA-Cw6) of the major histocompatibility complex have been strongly associated with psoriasis." (PMID 24069534, 2013). "The SNP in IL12B was replicated with 578 cases and 1422 controls, and the authors found a positive association with psoriasis." (PMID 24069534, 2013). "A subsequent GWAS with 1810 cases and 2522 controls found an association between SNPs in IL23R (rs7530511 and rs11209026) and IL12B (rs6887695 and rs3212227) and predisposition to psoriasis in Caucasian patients." (PMID 24069534, 2013). "In Caucasians, a GWAS (1446 cases and 1432 controls) showed the combination of rs3212227 and rs6887695 in IL12B as a risk haplotype in psoriasis." (PMID 24069534, 2013). "The SNPs rs11209026 in IL23R gene and rs3212227 in IL12B gene have also been studied in Japanese patients (143 cases and 100 controls), and the A allele (rs3212227) was more frequent in patients with psoriasis than in healthy subjects." (PMID 24069534, 2013). "Psoriasis has been associated with genes involved in the immune response, namely, TNFα, IL12B, and IL23R." (PMID 24069534, 2013). "Similar to IL23R, IL12B is also a shared susceptibility gene with other IBD-associated diseases such as psoriasis and ankylosing spondylitis, providing an explanation of the increased incidence of these extraintestinal manifestations in IBD patients." (PMID 22479607, 2012). "Genetic variants in the IL12B region have also been associated with the susceptibility to psoriasis, ankylosing spondylitis, and infectious diseases such as leprosy and tuberculosis." (PMID 22479607, 2012). "An insertion/deletion polymorphism in the promoter region of IL12B has been reported to be associated with psoriasis and cerebral malaria while two intronic SNP polymorphisms were associated to asthma." (PMID 18431485, 2008).
psoriasis (continued). "Recently, association of single-nucleotide polymorphisms (SNPs) within the interleukin-23 receptor gene (IL23R) and a gene encoding a subunit of its ligand, IL12B, have been reported to be associated with psoriasis." (PMID 19035472, 2008). "Additionally, the IL12B gene, which encodes the p40 subunit common to IL-12 and IL-23, has emerged as an important genetic factor in both psoriasis and AD, albeit through different biological pathways." (PMID 41465136, 2025). "Additionally, IL12B was linked to the modulation of Th1 immune responses, which are known to play a significant role in psoriasis-related inflammation." (PMID 39590306, 2024). "From a genetical point of view, the overlap between psoriasis and MetS may be explained by IL-12B, IL-23R, and IL-23A gene variants related to psoriasis susceptibility but also to risk for developing type II DM." (PMID 38003284, 2023). "Some polymorphisms identified in genes such as TNF, IL12RB2, and IL12B could be also involved in the production, differentiation, or activity of Tregs, pointing to a genetic background of Treg dysfunction in psoriasis." (PMID 37628670, 2023). "The identification of the type I cytokine receptor gene IL23R as genetic risk factor for psoriasis initially was a secondary finding: Variants at IL12B, a gene encoding a subunit shared by the cytokines IL–12 and IL–23, were found to be significantly associated with psoriasis in a GWAS." (PMID 38835412, 2023). "IL12B variants have been associated with both Crohn’s disease and psoriasis." (PMID 37426809, 2023). "Moreover, the IL12B is a known biomarker for single-nucleotide polymorphisms in psoriasis, and a monoclonal antibody against the IL-12/23 subunit is used clinically." (PMID 35393522, 2022). "A GWAS showed a reported psoriasis-associated SNP in the IL12B 3′ untranslated region (rs3212227)." (PMID 35707771, 2022). "Further insight into the elaborated psoriasis cytokine axis showed an impact of patients’ excessive body mass (defined both as visceral and overall adiposity) on the higher incidence risk of psoriasis among carriers of the IL12B gene polymorphism." (PMID 34445769, 2021). "Genetic variants near IL12B are associated with both psoriasis and Crohn's disease." (PMID 33748968, 2021). "In particular, the IBD3 locus involved in CD and UC, and the PSORS1 locus involved in psoriasis, were found in the 6P21 region, and the gene encoding the interleukin 23 receptor (IL-23R) and interleukin 12B (IL-12B) are both implicated in the pathogenesis of psoriasis and IBD." (PMID 33477990, 2021). "Moreover, genetic variations that encode subunits of cytokines (IL-12B, IL-23A) or cytokine receptors (IL-23R) have been associated with immune disorders such as psoriasis and psoriatic co-morbidities, including Crohn's disease and diabetes." (PMID 22185520, 2011). "Increased epidermal thickness is an important diagnostic hallmark of psoriasis and stable IL-12B knockdown seemed to result in a reduction in epidermal thickness by 27% (414 mm to 304 mm) in skin transduced with shIL12B-encoding lentiviral vectors compared to controls." (PMID 21352568, 2011). "Variation within IL23R and IL12B is associated with susceptibility to both psoriasis and PsA." (PMID 19035472, 2008). "In addition to this, polymorphism studies have shown relationships between the IL-12B and IL-23R genes and various autoimmune diseases such as multiple sclerosis, psoriasis, rheumatoid arthritis (RA), inflammatory bowel disease, ankylosing spondylitis, sarcoidosis, arthritis and Crohn’s disease." (PMID 41596568, 2026). "The association between IL12B gene polymorphisms and psoriasis susceptibility has also been reported in an Egyptian cohort study, in which the rs610604 in the IL12B gene exhibited a highly significant association with psoriasis in patients with early onset of the disease (less than 30 years)." (PMID 40343299, 2025).